ENSG00000259135 (novel transcript, antisense to SNX6)
Gene: Long non-coding RNA gene on chromosome 14 (34,545,808 to 34,562,387, forward strand). Ensembl gene ENSG00000259135.
Gene Ontology:
Molecular function: pre-mRNA 5'-splice site binding
Biological process: mRNA 5'-splice site recognition
Cellular component: U1 snRNP